IDH1 (isocitrate dehydrogenase (NADP(+)) 1)
Diseases named in the same sentence as IDH1 in open-access papers (continued):
Sharing a sentence is not in itself a finding about the gene and the disease.
glioma (continued). "Since IDH1 mutations are generally more common in low-grade gliomas, the general ratio of PC to GPC could serve as a prediction factor, such that elevated levels of PC and decreased levels of GPC would indicate high-level gliomas, such as GBM." (PMID 34068300, 2021). "Therefore, IDH1/2 mutated glioma shows the sensitivity of glutaminase inhibition in combination with radiotherapy." (PMID 34571995, 2021). "Combining with clinical parameters including grade, IDH1 mutation, and 1p19q co‐deletion status, we could predict the survival time of glioma patients more precisely." (PMID 34449972, 2021). "Seventy-one glioma cases were enrolled, including 30 carrying IDH1 mutation." (PMID 33472598, 2021). "The mutation of isocitrate dehydrogenase 1 (IDH-1) gene leads to the accumulation of D-2-hydroxyglutarate in glioma cells, which acts as agonist of glutamate receptors when the extracellular concentration of glutamate is not increased, contributing to hyperexcitability and seizure generation." (PMID 34262432, 2021). "Importantly, IDH-1/2 mutations pose an important anti-cancer strategy for hard-to-treat cancer types, these mutations occurring in ~ 70–80% of lower-grade gliomas and the majority of secondary glioblastomas and in up to 20% of patients with AML." (PMID 34717701, 2021). "Indeed, globally hypermethylated glioma cells (due to IDH1/2 mutation, another driver of the hypermethylator phenotype) are hypersensitive to DNA hypomethylating drugs." (PMID 33461589, 2021). "To determine how this molecular classification can assist in a more accurate diagnosis, we analyzed 8127 glioma samples (sequenced by F1 or F1CDx assays) and binned them into molecular subgroups based on IDH1/2 mutational status and codeletion of chromosomes 1p and 19q, as determined by F1/F1CDx." (PMID 33778493, 2021). "The high frequency of IDH1/2 mutations in gliomas and the resulting DNA hypermethylation may explain the contrasting results between mDNAsi and mRNAsi." (PMID 35069679, 2021). "That this could be indeed the case, is substantiated by a recent report showing in a glioma model that mutant IDH1 is associated with reduced levels of NAD(H), compared to the levels in IDH wildtypes." (PMID 35002914, 2021). "A large subset of diffusely infiltrative gliomas contains a gain-of-function mutation in isocitrate dehydrogenase 1 or 2 (IDH1/2mut) which produces 2-hydroxglutarate, an inhibitor of α-ketoglutarate-dependent DNA demethylases, thereby inducing widespread DNA and histone methylation." (PMID 34424450, 2021). "However, despite the wide variety of non-glioma cell lines with endogenous IDH1/2 mutations, there are very few comprehensive studies addressing metabolic changes in these models." (PMID 35028610, 2021). "Therefore, we aimed to investigate the association between oral microbiota and glioma grade and examine the relationship between the composition and functional features of malignancy-related oral microbiota and the glioma IDH1 mutation." (PMID 34733261, 2021). "Previous studies suggested that IDH1 mutation could be an essential contributor to cause the better survival of IDH-mutant glioma than the IDH wild type." (PMID 34961815, 2021). "Currently, the relationship between oral microbiota and the glioma IDH1 mutation is uncertain." (PMID 34733261, 2021). "Furthermore, an in vivo and in vitro study investigated the platelet aggregation and clotting time in the presence of IDH-1 mutation in gliomas." (PMID 34178693, 2021).
glioma (continued). "They showed joint variables derived from T1-weighted image (T1WI), T2 weighted image (T2WI), and contrast-enhanced T1WI imaging histograms and GLCM features could be used to detect IDH1-mutated gliomas." (PMID 33958734, 2021). "Both bioinformatics analysis and clinical validation have shown that IDH1 mutation could significantly alter gluconeogenesis and glycolysis, which contributes to the lower glucose consumption in IDH1mut gliomas." (PMID 33472598, 2021). "Studies performed on glioma cell models have successfully connected the widely known glioma marker, 2-hydroxyglutarate (2-HG) with the IDH1 mutation, as IDH-mutated cells gained a new, unique ability to convert α-KG into 2-HG, that IDH-wildtype glioma cells do not possess." (PMID 34068300, 2021). "IDH1 mutation might contribute to the lower glucose metabolism and good prediction of malignancy in gliomas." (PMID 33472598, 2021). "IDH1-R132H (mIDH1) catalyzes the production of 2-hrydroxyglutarate, eliciting epigenetic reprogramming of gene expression and is associated with better prognosis in glioma patients." (PMID 34168976, 2021). "Specifically, the abundance of glutamine in glioma further accelerates the tumor anabolism as glutamate converted from glutamine by glutaminase may be metabolized to D2HG in IDH1 mutated glioma cells accompanied by a loss of proper enzymatic activity." (PMID 34490096, 2021). "Within 2q33.3, which is also a locus associated with IDH1-mutated glioma, the target gene C2orf80 is 50 kb telomeric to IDH1, but whether or how C2orf80 interacts with IDH1 remains to be elucidated." (PMID 33936159, 2021). "The lower ALPS index in IDH1 wild-type gliomas may suggest an association between glymphatic dysfunction and tumor aggressiveness." (PMID 34631582, 2021). "Interestingly, IDH1/2 mutated gliomas appear to be more sensitive to genotoxic therapies than their wild-type counterparts." (PMID 34571995, 2021). "Finally, TRIM22 was increased in a cohort of primary GBM samples on a tissue microarray, and high expression of TRIM22 correlated with other clinical parameters associated with progressive gliomas, such as wild-type IDH1 status." (PMID 32814880, 2021). "The purpose of the present study was to test the possible utility of fractal analysis from MET uptake in patients with newly diagnosed gliomas for differentiating glioma, especially in relation to IDH1 mutation status, in a comparison with the conventional SUV parameters." (PMID 34743250, 2021). "It has been reported that an IDH1 mutation was potentially able to form glioma hypermethylation phenotype while IDH2 could promote acute myeloid leukemia." (PMID 35996504, 2021). "Besides, an individual patient would have a higher risk score if his pathologic type of glioma was an astrocytoma or if he carried a wildtype IDH1." (PMID 34858984, 2021). "Mukherjee and colleagues showed that the combination of ATRX loss and IDH1 R132 mutation might be sufficient for ALT activation in gliomas." (PMID 34069193, 2021). "Previous researches have indicated that the close relationship between IDH1 mutation and high survival rate also suggests that IDH1 may be a new epigenetic target for glioma therapy." (PMID 34597473, 2021). "The discovery of IDH1/2 mutations in glioma has fueled the classification of malignant gliomas at the phenotypic, molecular, and genetic levels, ultimately leading to the definition of three major glioma subtypes – mesenchymal, classical, and proneural." (PMID 34012965, 2021). "The IDH1 mutation in glioma cells weakened the CXCL2-mediated recruitment of neutrophils, which may be one of the reasons for the low malignancy of LGGs." (PMID 34211978, 2021). "In glioma, tumour grade IV is positively associated with the number of intronic junctions per sample (P = 1.1 × 10−5), whereas tumour grade II (P = 2.9 × 10−8) and presence of IDH1 mutation (P = 0.8 × 10−3) were negatively associated." (PMID 34891161, 2021).
glioma (continued). "IDH1 mutation significantly affects the prognosis of glioma patients, so the difference in IDH1 mutation among the immune subtypes may be one of the factors affecting the survival time of patients." (PMID 34603319, 2021). "In addition, patients with IDH1-mutated glioblastomas show better outcomes than IDH1 wild-type gliomas of a lower grade." (PMID 33918828, 2021). "Elevated myo-inositol, high Gln and Glu dependency and decrease in GSH could all indicate high grade glioma, while high 2-HG concentration could be associated with IDH1 mutation and therefore better prognosis." (PMID 34068300, 2021). "The discovery of mutations in isocitrate dehydrogenase 1 (IDH1) or isocitrate dehydrogenase 2 (IDH2) genes in glial brain tumors critically shaped the understanding of the clinical importance of molecular differences in gliomas." (PMID 33216206, 2021). "As somatic missense mutations in the IDH1 gene are frequently found in gliomas and have been related with better patient survival, several transgenic zebrafish lines expressing various IDH1 mutations have been established to clarify their role in tumor development." (PMID 33802571, 2021). "The commonest IDH1 mutation in gliomas affects codon 132 and encodes IDH1(R132H)." (PMID 34203535, 2021). "IDH1 mutations lead to better overall survival in gliomas patients." (PMID 34070746, 2021). "However, as more aggressive mutations are acquired in later stages of glioma, the IDH1 mutation has been shown to be converted to a passenger mutation which renders glioma cells to proliferate in a mutant IDH-independent manner." (PMID 34356864, 2021). "Comprehensive studies reporting metabolic changes with respect to mutIDH have mainly focused on glioma, despite the availability of cell lines with stable mutIDH1/2 expression for several other cancers with high rates of IDH1/2 mutations; e.g., AML, chondrosarcoma, and ICC." (PMID 35028610, 2021). "The IDH1-R132H mutation is involved in the early gliomagenesis; however, after carcinogenesis complete, it is considered a radiosensitizing gene and a better prognostic factor that predicts favorable outcome in glioma patients." (PMID 33981597, 2021). "IDH1 hotspot mutations are rare events in human cancer but prevalent in glioma." (PMID 34440884, 2021). "We speculate that the spread of IDH1 wild-type gliomas is associated with greater disruption to the flow of interstitial fluid and, consequently, lower glymphatic function." (PMID 34631582, 2021). "Indeed, mutations in IDH1/2 and 1p19q codeletion characterize the majority of low-grade gliomas (LGGs) and define a subtype associated with a favorable outcome." (PMID 33477668, 2021). "Although they were thought to be virtually exclusive in glioma, further mutational analyses revealed IDH1 and IDH2 mutations, as well as IDH2 Arg140 mutations, in various cancer types such as myeloid neoplasia, chondrosarcoma, cholangiocarcinoma, and prostate cancer." (PMID 34440884, 2021). "Furthermore, IDH1 mutation is associated with the reduction in cell survival, proliferation and invasion of glioma by decreasing the WNT signaling." (PMID 34070746, 2021). "Further analyses of 923 gliomas revealed 34 and 1% of IDH1 and IDH2 mutations, respectively." (PMID 35996504, 2021). "Previous studies report that IDH1 mutations are linked to more prolonged survival and may serve as an independent prognosis biomarker for low-grade gliomas." (PMID 34081618, 2021). "Interestingly, the combination of TBR/ADC had a significantly higher diagnostic accuracy than that of each single imaging method in both glioma grading and predicting the mutation status of IDH1, hTERT, and EGFR." (PMID 34912706, 2021). "Conclusion: the presence of non-canonical IDH1 mutations could be associated with improved survival among patients with IDH1 mutated grade II–III glioma." (PMID 33669525, 2021).
glioma (continued). "Indeed, most (>70%) diffuse grade II gliomas carry a recurrent missense mutation in the IDH1 or IDH2 (isocitrate dehydrogenase 1/2) genes, with IDH1R132H being the most commonly identified mutation (90%)." (PMID 33925547, 2021). "So, IDH1 mutation has been applied in molecular typing and comprehensive diagnosis for gliomas." (PMID 33472598, 2021). "Tumor-specific molecular alterations, such as isocitrate dehydrogenase 1 (IDH1) mutation and the codeletion of chromosome arms 1p and 19q (1p/19q codeletion), could serve as prognostic indicators or therapeutic targets for glioma patients." (PMID 34956239, 2021). "Molecular classification of gliomas has been revised due to the discovery of the IDH1 mutation." (PMID 34422648, 2021). "In IDH1/2 mutated gliomas, the high concentration of D-2-HG could suppress the function of KDM4A, KDM4B, and KDM4C (also known as JmjC-KDM2A, JmjC-KDM2B, and JmjC-KDM2C), and increase histone methylation levels, such as H3K9me3, H3K9me2, H3K36me3, and H3K4me3." (PMID 34571995, 2021). "Dominant IDH1/2 mutations have been found in patients with gliomas and acute myeloid leukemia." (PMID 34884868, 2021). "Thus, we sought to develop tools for organellar quantification of lipids, which can be applied to determine the lipid profile changes due to IDH1 mutation in organelles of glioma cells." (PMID 33504762, 2021). "In one study, metabolic changes were studied in gliomas patients with IDH1 mutation." (PMID 34150663, 2021). "The recent success of the IDH1 mutation-specific vaccine in treating IDH1-mutated gliomas may open new doors for the treatment of IDH-mutant gliomas." (PMID 34067729, 2021). "IVIM-DWI presented efficacy in differentiating glioma grading and IDH1 mutation status." (PMID 33795525, 2021). "Although many molecular biomarkers are linked to glioma, such as isocitrate dehydrogenase enzyme 1/2 (IDH1/2) mutation and epidermal growth factor receptor (EGFR) overexpression, their reliability and clinical significance are still controversial and need more research." (PMID 34222249, 2021). "In addition, we tried to explore the relationship between the methylation level of the lncRNA promoter region and IDH1 mutations in glioma samples." (PMID 33828990, 2021). "This study may provide evidence for the application of IVIM-DWI and 3D pCASL in glioma grading and IDH1 mutation predication." (PMID 33795525, 2021). "IDH1 is believed to be the most frequent mutation site in glioma." (PMID 33795525, 2021). "The observation that patients harbouring non-R132H IDH1/2-mutated gliomas have longer survival is of importance for clinical practice as the specific IDH1/2 mutation could alter patient prognostication." (PMID 33740099, 2021). "For example, carcinomas with isocitrate dehydrogenase 1 (IDH1) mutations, such as gliomas and sarcomas, tend to downregulate NAPRT levels through hypermethylation of the NAPRT promoter, thereby blocking the NA–NAPRT pathway, which makes them dependent on NAMPT for NAD replenishment." (PMID 34068917, 2021). "Thus, IDH1-R132H causes a significant reduction in the proliferation, migration and invasiveness of gliomas, accompanied by an increase in apoptotic cell death." (PMID 34070746, 2021). "We also found that low expression of STOX1 was more often found in IDH1 wild-type gliomas, suggesting that STOX1 may be functionally associated with IDH1 status." (PMID 34722888, 2021). "In contrast, gliomas carrying wild-type IDH1 are often more aggressive and thus more likely to cause destruction of brain networks, which may add barriers to the spread of epileptic discharges." (PMID 34220689, 2021). "IDH1 mutations are one of the earliest detectable genetic damages in low-grade gliomas." (PMID 34070746, 2021).
glioma (continued). "For example, IDH1/2 mutations in adult gliomas and histone H3.1 and H3.3 mutations in pediatric high grade gliomas were shown to be clonal for their respective subtypes, and developing therapies targeting these genetic alterations would reduce the risk of antigen-escape." (PMID 34168976, 2021). "Moreover, mutation of isocitrate dehydrogenase 1 (IDH1) occurs frequently, which results in accumulation of the metabolic byproduct 2-hydroxy-glutarate (2-HG) in glioma." (PMID 33718165, 2021). "Our survey was restricted to 25 cancer types available from the International Cancer Genome Consortium database and IDH1 mutations occur in a wider range of cancer types than depicted here, including oligodendro-gliomas, astrocytomas, secondary glioblastomas and acute myeloid leukemia." (PMID 33094325, 2021). "Moreover, TERT promoter mutations were observed in almost all gliomas with concurrent total 1p/19q loss and IDH1/2 mutations (98%)." (PMID 34638714, 2021). "Based on clinical glioma specimen and unique patient-derived cell lines carrying the endogenous IDH1 mutation, we report that IDH1m astrocytomas specifically rely on cystathionine-γ-lyase (CSE, also known as cystathionase, CTH gene) to increase their cysteine pool for de novo GSH synthesis." (PMID 34250481, 2021). "Somatic mutations in IDH1 cause disturbances in cell metabolism, a common feature of gliomas." (PMID 34884868, 2021). "In the present study, we established a novel assay that applies liquid biopsy targeting the ctDNA in CSF using chip-based digital PCR (dPCR) for detecting the glioma-specific diagnostic driver mutations such as IDH1 R132H (IDH1), H3F3A K27M (H3 K27M), and TERT promoter (pTERT) mutations." (PMID 33417137, 2021). "Since recent data have shown that glioblastoma cancer stem cells can generate cells contributing to vessel formation, we performed double immunostaining using antibodies that selectively recognize the mutated proteins EGFRvIII and IDH1-R132H, histological hallmarks of tumor-derived glioma cells." (PMID 34272603, 2021). "Gliomas with IDH1 mutations tend to have a more favorable prognosis." (PMID 34422648, 2021). "In addition, IDH1-mutated glioma cells in metabolic stress show increased levels of autophagy in order to provide substrates for energy production." (PMID 34069550, 2021). "IDH1 wild-type gliomas and gliomas with larger peritumoral brain edema volumes were associated with a lower ALPS index, which may reflect impaired glymphatic function." (PMID 34631582, 2021). "IDH1 mutation could dramatically affect tumor metabolism and epigenetics, as proline is upregulated simultaneously with 2-HG in IDH1mut gliomas in our previous study." (PMID 33472598, 2021). "The interstitial level of GABA appears crucial to attenuate glioma growth in vivo: an analysis with ultra-sensitive 3-tesla magnetic resonance demonstrated that GABA levels are decreased in IDH1-mutated low-grade glioma foci compared to the contralateral hemisphere of patients." (PMID 34199968, 2021). "However, our results showed that here was no statistical difference in the promoter methylation levels of LINC02875 and PCBP1-AS1 in glioma samples with different IDH1 mutation states." (PMID 33828990, 2021). "In GBM, IDH1 mutations can predict whether the tumors are secondarily developed from lower-grade gliomas because IDH1 mutations are rarely found in primary GBM." (PMID 33767690, 2020). "However, previous studies have established gene signatures to divide the IDH1 mutation glioma patients with different clinical features into various groups." (PMID 33229627, 2020). "IDH1 mutation shows diagnostic, prognostic, and predictive value in gliomas." (PMID 33247679, 2020).